XRN1 (5'-3' exoribonuclease 1)
Description:
Major 5'-3' exoribonuclease involved in mRNA decay. Required for the 5'-3'-processing of the G4 tetraplex-containing DNA and RNA substrates (By similarity). The kinetic of hydrolysis is faster for G4 RNA tetraplex than for G4 DNA tetraplex and monomeric RNA tetraplex (By similarity). Plays a role in replication-dependent histone mRNA degradation. May act as a tumor suppressor protein in osteogenic sarcoma (OGS).
Synonyms: SEP1
Tractability: Antibody: its Gene Ontology location is reachable by antibodies, with high confidence; the Human Protein Atlas places it where antibodies can reach. PROTAC: ubiquitination databases record sites on it; its protein half-life has been measured.
Gene: Protein-coding gene on chromosome 3 (142,306,607 to 142,448,087, reverse strand). Ensembl gene ENSG00000114127.
Subcellular location: Cytoplasm
Subcellular location (Human Protein Atlas): Cytosol; Plasma membrane
Pathways (Reactome):
Metabolism of RNA: Butyrate Response Factor 1 (BRF1) binds and destabilizes mRNA; Tristetraprolin (TTP, ZFP36) binds and destabilizes mRNA; mRNA decay by 5' to 3' exoribonuclease
Disease: Dengue Virus Genome Translation and Replication
Gene Ontology:
Molecular function: 5'-3' RNA exonuclease activity; protein binding; RNA binding; telomerase RNA binding; G-quadruplex DNA binding; G-quadruplex RNA binding; 5'-3' exonuclease activity; exonuclease activity; nucleic acid binding
Biological process: histone mRNA catabolic process; mRNA catabolic process; nuclear mRNA surveillance; nuclear-transcribed mRNA catabolic process; rRNA catabolic process; deadenylation-dependent decapping of nuclear-transcribed mRNA; negative regulation of telomere maintenance via telomerase; nuclear-transcribed mRNA catabolic process, deadenylation-dependent decay; cellular response to cycloheximide; cellular response to puromycin; negative regulation of translation; response to testosterone; RNA metabolic process
Cellular component: cytosol; membrane; plasma membrane; P-body; RNA decapping complex; cytoplasm; dendrite; neuronal cell body; nucleus
Genetic constraint (gnomAD): Loss-of-function variants: 54 observed, 181.45 expected, observed/expected ratio (o/e) 0.3, 90% interval 0.24 to 0.37. The upper end of that interval is the gene's LOEUF score, 0.37, which puts it in group 1 of 6, group 1 being the genes least tolerant of losing a copy. Missense variants: 1,570 observed, 1,891.9 expected, observed/expected ratio (o/e) 0.83, 90% interval 0.8 to 0.87. Synonymous variants: 594 observed, 629.54 expected, observed/expected ratio (o/e) 0.94, 90% interval 0.88 to 1.01.
Homologues: Orthologues: chimpanzee XRN1 (99% identical), macaque XRN1 (98% identical), dog XRN1 (94% identical), pig XRN1 (93% identical), rabbit XRN1 (92% identical), rat Xrn1 (88% identical), mouse Xrn1 (88% identical), zebrafish xrn1 (64% identical), Caenorhabditis elegans xrn-1 (34% identical), Drosophila melanogaster pcm (33% identical). Paralogues in human: XRN2 (18% identical).
Diseases named in the same sentence as XRN1 in open-access papers:
XRN1 is named in the same sentence as 24 diseases in open-access papers, as found by Europe PMC text mining. Sharing a sentence is not in itself a finding about the gene and the disease. The quoted sentences say what the papers report.
viral infection (13 papers, 2014 to 2025). "XRN1, a highly efficient host exonuclease, can cleave 5’ monophosphates from the 5’ to 3’ direction, mediating mRNA cleavage in many viral infections." (PMID 36153658, 2022). "The expressive proteins of IRF3 are equal in virus-infected XRN1 KO cells and A549 control cells, but p-IRF3 significantly increases in XRN1 KO cells after viral infection." (PMID 34311580, 2021). "SfRNA is a product of an incomplete degradation of genomic RNA by the host 5′–3′ exoribonuclease XRN1 and sfRNA is involved in viral infection and host cell response modulation." (PMID 28603696, 2017). "Although subclass 1b xrRNAs are resistant to Xrn1 in vitro, their function in the context of viral infection and pathogenesis remains unclear." (PMID 32994331, 2020). "The involvement of XRN1 or XRN4 in viral infections has been reported." (PMID 26779163, 2015). "The repression of XRN1 activity by HCV or BVDV infection suggests that cellular mRNA decay may be dramatically dysregulated during viral infection." (PMID 25747802, 2015). "Notably, in studies of viral infection of human cells, Xrn1-dependent degradation of mRNAs cleaved by viral endonucleases has been demonstrated to trigger the translocation of RNA binding proteins to the nucleus, where they repress RNA Pol II binding to promoters." (PMID 40107731, 2025). "Interestingly, the role of XRN1 and DCPs in viral infections varies greatly." (PMID 32034313, 2020). "Altogether, our findings indicate that Xrn1 might be a critical RNA virus restriction factor, and it is likely targeted by SARS-CoV-2 N protein and HMPV M2-1 during viral infections." (PMID 40422074, 2025). "In addition, localization of AGO1, another PB marker, remains unchanged upon viral infection, indicating that redistribution of XRN1-DCPs into vRC is independent of PB-related functions." (PMID 32034313, 2020). "XRN1 RNA expression was the lowest in salivary glands and was not altered by virus infection." (PMID 28753642, 2017).
prostate carcinoma (7 papers, 2015 to 2025). A carcinoma that arises from epithelial cells of the prostate gland. "Furthermore, XRN1 was suggested to play an important role in prostate cancer via diverse miRNA-regulatory functions." (PMID 38689093, 2024). "Consequently, XRN1 can ameliorate the effects of IFNγ-induced invasion in vitro and metastasis in vivo of prostate cancer." (PMID 38689093, 2024). "Thus we revealed the AR-miR-204-XRN1-miR-34a positive feedback loop and a dual function of miR-204/XRN1 axis in prostate cancer." (PMID 25797256, 2015). "In response to increased mRNA decay mediated by XRN1 and DDX6, DHX9 emerges as a significant target molecule in acquired resistance to bortezomib in PC3 prostate cancer cells." (PMID 39799471, 2025). "Expression of miR-204-5p was repressed by targeting XRN1 and TRKB in prostate cancer and EC, respectively." (PMID 34076696, 2021). "Expression of miR-204 is repressed by its targets XRN1 and TRKB in prostate cancer and endometrial carcinoma, respectively; therefore, they establish an oncogenic feedback loops that play an important role promoting development of cancer." (PMID 27438705, 2016).
Flavivirus Infections (5 papers, 2014 to 2025). Infections with viruses of the genus FLAVIVIRUS, family FLAVIVIRIDAE. "ZFP36L2 inhibited flavivirus infection solely through the 5′-3′ XRN1 RNA decay pathway, whereas ZFP36L1 inhibited JEV infection via the 5′-3′ XRN1 and 3′-5′ RNA exosome RNA decay pathways." (PMID 39972499, 2025). "During flavivirus infection, viral genomic RNA is subjected to degradation by the host 5′−3′ exoribonuclease Xrn1 (reviewed by Slonchak and Khromykh)." (PMID 38059479, 2023). "So Xrn1 stalls on this structures and creates a large amount of degradation intermediates in host cells, named subgenomic flavivirus RNA (sfRNA) or Xrn1-resistant RNAs (xrRNAs), as a specific feature of flavivirus infection." (PMID 30740112, 2018). "During flavivirus infections, short flavivirus RNAs (sfRNAs) are produced by the incomplete degradation of viral RNA by the host-cell exonuclease Xrn1." (PMID 29813061, 2018). "In contrast with the antiviral mechanism of ZFP36L1 against flaviviruses in which ZFP36L1 recruits both the 5′-3′ XRN1 and 3′-5′ RNA exosome pathways to degrade flavivirus RNA, ZFP36L2 impedes flavivirus infection through a 5′-3′ XRN1-mediated RNA decay pathway." (PMID 39972499, 2025). "ZFP36L2 restricts flavivirus infection by approximately tenfold through XRN1-mediated antiviral activity, suggesting that this pathway may partially, but not completely, accounts for ZFP36L2’s antiviral effect." (PMID 39972499, 2025). "The feedback of the repression of XRN1 to other factors in the 5'–3' decay pathway may be due to direct protein-protein interactions between XRN1 and decapping enzymes as well as through P-bodies (which, interestingly, become disrupted in flavivirus infections)." (PMID 24473339, 2014).
dengue virus infection (3 papers, 2014 to 2019). "Indeed, studies of Dengue and Kunjin virus infections showed that sfRNA production stabilizes mRNAs by inhibiting Xrn1." (PMID 24692447, 2014).
oral cancer (2 papers, 2019 to 2020). "XRN1 was expressed at significantly lower levels in the oral cancer cell lines compared to normal HOK cells." (PMID 31940341, 2020). "In conclusion, next-generation sequencing analysis revealed that a total of 13 genes (RRP43, RRP42, CSL4, TRF4, Mtr4, RRP6, MPP6, CNOT2, CNOT3, SKI2, Ski3, EDC4, and XRN1) involved in the mRNA degradation pathway were upregulated by PPARα activation in oral cancer cells." (PMID 31724941, 2019).
bone osteosarcoma (1 paper, 2020). A usually aggressive malignant bone-forming mesenchymal neoplasm arising from the bone. "To determine whether XRN1-DCPs utilize the RNA-induced silencing complex (RISC) to target vRNA for degradation, we used human bone osteosarcoma epithelial (U-2 OS) cells stably co-expressing mRFP-DCP1a and EGFP-AGO1." (PMID 32034313, 2020).
Hyperglycemia (1 paper, 2022). An increased concentration of glucose in the blood. "No XRN1 variants in humans have been associated with obesity, but a recent study investigating forebrain-specific Xrn1 knockout mice found that lack of Xrn1 in neurons led to obesity, hyperphagia, leptin resistance and hyperglycemia." (PMID 35330733, 2022).
lung carcinoma (1 paper, 2025). "First, we transfected wild type (WT) and exonuclease deficient (XRN1 KO) A549 human lung carcinoma cells with the RNase L activator, 2–5A." (PMID 40568168, 2025).
Obesity (1 paper, 2022). Accumulation of substantial excess body fat. "In our study, we identified a heterozygous missense variant in XRN1 of uncertain significance in a participant with isolated obesity." (PMID 35330733, 2022).
osteosarcoma (1 paper, 2015). A usually aggressive malignant bone-forming mesenchymal neoplasm, predominantly affecting adolescents and young adults. "Along these lines, it is interesting to note that XRN1 has been previously implicated as a possible tumor suppressor gene in osteosarcoma." (PMID 25747802, 2015).
poliovirus infection (1 paper, 2016). An disease or disorder caused by infection with Enterovirus C. "As an additional protection, the major 5′→3′ exonuclease, Xrn1, is degraded during poliovirus infection, preventing 5′→3′ digestion of unlinked vRNAs (discussed further in Section 5)." (PMID 27999393, 2016). "The PB proteins Dcp1a and Xrn1 are degraded during poliovirus infection." (PMID 27999393, 2016).
Rotavirus infection (1 paper, 2016). Infection with any of the rotaviruses. "A recent report showed that rotavirus infection triggers a significant time-dependent decline of PBs components XRN1, DCP1, Pan3, but not GW182." (PMID 27367717, 2016). "Pan3, but not XRN1 and DCP1, undergoes accelerated turn over in response to rotavirus infection, while XRN1 and DCP1 were translocated to the nucleus, as well as PABP." (PMID 27367717, 2016).
ZIKV infection (1 paper, 2021). "Furthermore, XRN1 is halted in its degradative action by two structured XRN-1-resistant RNA elements (xrRNAs) on ZIKV, xrRNA1 and xrRNA2 which protect the remaining 3′UTR leading to the accumulation of sfRNAs during ZIKV infection." (PMID 33810028, 2021).
infection (23 papers, 2014 to 2025). The state of being infected such as from the introduction of a foreign agent such as serum, vaccine, antigenic substance or organism. "To determine if this mechanism is also sufficient to explain the loss of Pol II occupancy during MHV68 infection, we depleted Xrn1 and Dis3L2 individually or in tandem using siRNAs." (PMID 32032393, 2020). "Since sfRNA levels represent a balance between Xrn-1-dependent biogenesis and sfRNA degradation, we next investigated whether ZIKV-TL.PK and ZIKV-p.2.5′ cause a loss of Xrn-1 resistance during infection resulting in decreased biogenesis." (PMID 37417764, 2023). "Furthermore, no intermediate degradation byproducts from viral genome to the sfRNA were detected during infection even in the XRN1-deficient cells." (PMID 30048535, 2018). "In this study, we examined the distribution of ZFP36L2, XRN1, and viral dsRNA during infection, with confocal imaging revealing their colocalization within the RCs." (PMID 39972499, 2025). "Inhibition of both XRN1 and other cellular exonucleases alters global cellular mRNA stability throughout infection." (PMID 39082815, 2024). "RNAs that are able to prevent degradation by the 5’–3’ exoribonuclease Xrn1 have emerged as crucial structures during infection by an increasing number of RNA viruses." (PMID 37749116, 2023). "A549 XRN1 KO cells were used for viral growth kinetic studies and infected at a multiplicity of infection (MOI) of 0.01 in a multicycle experiment." (PMID 34311580, 2021). "The H1N1 viruses tested (WSN, PR8, and CA04) showed similar infection levels in A549 control cells and A549 XRN1 KO cells at 8 h.p.i., based on viral NP protein expression." (PMID 34311580, 2021). "There was higher expression of IFN-β, IFIT1, IFIT3, ISG15, and IRF7 mRNA in A549 XRN1 KO cells after 8 h of infection with various virus strains, including WSN (H1N1), PR8 (H1N1), CA04 (H1N1), and HK4801 (H3N2)." (PMID 34311580, 2021). "The localization of NS1 and XRN1 in A549 cells during a time course of WSN infection was studied using anti-XRN1 (green color), anti-NS1 (red color), and anti-DCP1A (purple color) antibodies in an immunofluorescence assay (IFA) by confocal microscopy." (PMID 34311580, 2021). "Despite these previous reports, the broad antiviral role of XRN1 and DCPs during infection of cytoplasmic-replicating RNA viruses remains elusive." (PMID 32034313, 2020). "Mechanistically, infection with RNA viruses induced the enrichment of XRN1 and DCPs in viral replication complexes (vRCs), hence forming distinct cytoplasmic aggregates." (PMID 32034313, 2020). "Knocking-down (KD) the XRN1 expression by up to 95% in HEK293T cells continued to increase the abundance of sfRNA throughout the 48-h infection period." (PMID 30048535, 2018). "The stalling of XRN1 at this structure results in the accumulation of large amounts of a short 3’ UTR-derived subgenomic flavivirus ‘sfRNA’ during infection." (PMID 25747802, 2015). "In infection with flaviviruses such as Zika, dengue, and West Nile virus, XRN1 is stalled and blocked from continuing degradation at the site of the viral mRNA 3′ untranslated region (3′-UTR) due to the presence of pseudoknots or stem loops, which are referred as XRN1-resistant structures (xrRNAs)." (PMID 34311580, 2021). "The significance of the OST enrichment is currently unknown, although the OST complex has been shown to be critical for infection with flaviviruses, which depend on Xrn1 for the production of a subgenomic viral noncoding RNA." (PMID 30281021, 2018). "For instance, 5′→3′ RNA degradation is inhibited during infection through cleavage of decapping enzymes and Xrn1, but it is unclear whether exosomes, which participate in 3′→5′ RNA degradation, remain intact." (PMID 27999393, 2016). "Since targeting miR-122 is currently in clinical trials as a potential anti-HCV therapy, it appears that the viral RNA on its own may be highly targeted by XRN1 during infection." (PMID 25747802, 2015).
infection (continued). "Ultimately, this repression of XRN1 dysregulates cellular mRNA decay and likely prevents or significantly alters changes in gene expression which promote the proper cellular response to infection." (PMID 25747802, 2015). "Therefore we conclude that XRN1 repression is a highly conserved and important facet of infections by disparate members of the Flaviviridae." (PMID 25747802, 2015). "However, 2Apro-mediated disruption of PB was surprising, as we have previously determined it does not cleave the three PB constituents we found that undergo degradation during infection (Xrn1, Dcp1a, or Pan3)." (PMID 26610553, 2015). "Infections using a WNVKUN harboring a C10519→G point mutation in WNVKUNxrRNA1 results in a significant and reproducible decrease in sfRNA1 formation, corresponding with the incomplete loss of Xrn1 resistance we observe in vitro." (PMID 24692447, 2014). "We did not observe resistance from the DB elements in vitro; if they confer Xrn1 resistance during infection this may require interaction with a protein factor." (PMID 24692447, 2014). "Besides, gene expression analysis revealed a significantly higher expression of XRN1 in infected individuals compared to the healthy controls along with a comparatively higher pXRN1 during the course of infection suggesting evolutionary fitness of the virulent EMP gene against the targeting miRNA." (PMID 36941394, 2023). "We compared IFN-β-related host antiviral response during infection of WSN and WSN DelNS1-M-A14U (WSN DelNS1) viruses in the A549 control and A549 XRN1-KO cells." (PMID 34311580, 2021). "Here, we present evidence that the IRF3 mRNA of XRN1 KO cells upon WSN, PR8, CA04, and HK4801 infection are similar to that of A549 control." (PMID 34311580, 2021). "We have also measured IFN and ISG mRNA expression in A549 control cells and A549 XRN1 knockout cells, but after poly(I:C) treatment instead of WSN infection." (PMID 34311580, 2021). "As for positive strand viruses, infection with EMCV and poliovirus (PolioV) at early time points, similarly stimulated the aggregation of XRN1 and DCP1a." (PMID 32034313, 2020). "Over the course of infection, these sfRNAs accumulate in the cell as a result of an incomplete viral genome degradation of the 3′ UTR by the host 5′ to 3′ exoribonuclease, Xrn1." (PMID 33080971, 2020). "The flavivirus WNV reduces PB assembly during the course of infection through the sequestration of several PB components such as LSm1, GW182, Xrn1, DDX3, and DDX6 to viral replication factories (RFs)." (PMID 31681621, 2019). "In order to expand the observation of viral 5’ UTR-induced repression of XRN1/mRNA stabilization, we measured global mRNA decay rates in mock infected and HCV infected Huh7.5 cells after 120 hours at which point the infection rate was ∼70%." (PMID 25747802, 2015). "A previous study reported the antiviral activity of the cellular XRN1–DCP1/2 complex and revealed that infection with RNA viruses enriches XRN1 and DCPs in viral RCs; this phenomenon is not correlated with the essential localization and function of PBs." (PMID 39972499, 2025). "Treatment with XRN1 resulted in partial degradation of refolded in vitro transcribed 3’UTRs of PaRV, PCV, BinJV and KRBV and production of sfRNAs that had the same length as those detected in infection." (PMID 35277507, 2022). "Assessment of the proportion of noncapped RNAs in extracellular virus particles by XRN-1 degradation revealed that 24 h after infection the majority of RNAs from released SINV particles were capped." (PMID 36069441, 2022). "XRN1 is stalled at the 5′-UTR due to binding of hsa-miR-122 at the seed sequence site and the presence of stem loops during Flaviviridae hepatitis C virus (HCV) infection (25, –, 28)." (PMID 34311580, 2021). "Infection with another negative-sense virus, SeV was also found to induce the colocalization of XRN1 with vRC." (PMID 32034313, 2020).